ATP13A2 (ATPase cation transporting 13A2)
Description:
ATPase which acts as a lysosomal polyamine exporter with high affinity for spermine. Also stimulates cellular uptake of polyamines and protects against polyamine toxicity. Plays a role in intracellular cation homeostasis and the maintenance of neuronal integrity. Contributes to cellular zinc homeostasis. Confers cellular protection against Mn(2+) and Zn(2+) toxicity and mitochondrial stress. Required for proper lysosomal and mitochondrial maintenance. Regulates the autophagy-lysosome pathway through the control of SYT11 expression at both transcriptional and post-translational levels. Facilitates recruitment of deacetylase HDAC6 to lysosomes to deacetylate CTTN, leading to actin polymerization, promotion of autophagosome-lysosome fusion and completion of autophagy. Promotes secretion of exosomes as well as secretion of SCNA via exosomes. Plays a role in lipid homeostasis.
Synonyms: PARK9; HSA9947; CLN12; KRPPD; SPG78
Tractability: Small molecule: a structure with a bound ligand is known. Antibody: UniProt predicts a signal peptide or a membrane-spanning region. PROTAC: ubiquitination databases record sites on it; its protein half-life has been measured.
Gene: Protein-coding gene on chromosome 1 (16,985,958 to 17,011,928, reverse strand). Ensembl gene ENSG00000159363.
Subcellular location: Lysosome membrane; Late endosome membrane; Endosome, multivesicular body membrane; Cytoplasmic vesicle, autophagosome membrane
Pathways (Reactome):
Transport of small molecules: Ion transport by P-type ATPases
Gene Ontology:
Molecular function: ABC-type polyamine transporter activity; phosphatidic acid binding; phosphatidylinositol-3,5-bisphosphate binding; polyamine transmembrane transporter activity; protein binding; ATP hydrolysis activity; ATPase-coupled monoatomic cation transmembrane transporter activity; cupric ion binding; manganese ion binding; zinc ion binding; ATP binding; nucleotide binding; P-type ion transporter activity; P-type transmembrane transporter activity
Biological process: autophagosome organization; autophagosome-lysosome fusion; autophagy; cellular response to manganese ion; cellular response to oxidative stress; extracellular exosome biogenesis; intracellular calcium ion homeostasis; intracellular iron ion homeostasis; intracellular zinc ion homeostasis; lipid homeostasis; lysosomal transport; polyamine transmembrane transport; positive regulation of exosomal secretion; positive regulation of gene expression; positive regulation of protein secretion; protein localization to lysosome; regulation of autophagosome size; regulation of lysosomal protein catabolic process; regulation of macroautophagy; regulation of mitochondrion organization; regulation of protein localization to nucleus; spermine transmembrane transport; cellular response to zinc ion; intracellular monoatomic cation homeostasis; monoatomic ion transmembrane transport; and 6 more
Cellular component: autophagosome; late endosome; late endosome membrane; lysosomal membrane; lysosome; multivesicular body; neuron projection; neuronal cell body; transport vesicle; vesicle; lysosomal lumen; membrane; multivesicular body membrane; autophagosome membrane; vesicle membrane
Genetic constraint (gnomAD): Loss-of-function variants: 83 observed, 139.68 expected, observed/expected ratio (o/e) 0.59, 90% interval 0.5 to 0.71. The upper end of that interval is the gene's LOEUF score, 0.71, which puts it in group 2 of 6, group 1 being the genes least tolerant of losing a copy. Missense variants: 1,402 observed, 1,631.6 expected, observed/expected ratio (o/e) 0.86, 90% interval 0.82 to 0.9. Synonymous variants: 663 observed, 708.47 expected, observed/expected ratio (o/e) 0.94, 90% interval 0.88 to 1.
Gene-disease validity (ClinGen):
ClinGen rates the evidence that ATP13A2 causes each of these diseases.
Kufor-Rakeb syndrome (autosomal recessive): Definitive. Kufor-Rakeb syndrome (KRS) is a rare genetic neurodegenerative disorder characterized by juvenile Parkinsonism, pyramidal degeneration (dystonia), supranuclear palsy, and cognitive impairment.
Homologues: Orthologues: macaque ATP13A2 (91% identical), chimpanzee ATP13A2 (91% identical), pig ATP13A2 (89% identical), guinea pig ATP13A2 (87% identical), dog ATP13A2 (86% identical), mouse Atp13a2 (85% identical), rat Atp13a2 (85% identical), tropical clawed frog atp13a2 (52% identical), rabbit ATP13A2 (52% identical), zebrafish atp13a2 (51% identical), Drosophila melanogaster anne (37% identical), Caenorhabditis elegans catp-6 (36% identical), and 7 more. Paralogues in human: ATP13A3 (41% identical), ATP13A4 (39% identical), ATP13A5 (38% identical), ATP13A1 (25% identical), ATP2B3 (18% identical), ATP2B1 (17% identical), ATP2B2 (17% identical), ATP2B4 (17% identical), ATP2A3 (16% identical), ATP1A2 (16% identical), ATP2A1 (16% identical), ATP1A3 (16% identical), and 9 more.
Diseases named in the same sentence as ATP13A2 in open-access papers:
ATP13A2 is named in the same sentence as 95 diseases in open-access papers, as found by Europe PMC text mining. Sharing a sentence is not in itself a finding about the gene and the disease. The quoted sentences say what the papers report.
Kufor-Rakeb syndrome (119 papers, 2010 to 2026). "ATP13A2 mutations are also associated with Kufor–Rakeb syndrome (KRS), a rare form of autosomal‐recessive hereditary parkinsonism with dementia." (PMID 39925015, 2025). "Previously, other proteins from the P-type ATPases have been identified in a broad range of diseases, including loss-of-functions mutations in ATP13A2 as cause for the severe parkinsonism Kufor-Rakeb syndrome." (PMID 40676227, 2025). "Mutations in the ATP13A2 gene were identified as the cause of Kufor-Rakeb syndrome (KRS), a juvenile-onset form of Parkinson’s disease (PD)." (PMID 41253848, 2025). "Kufor–Rakeb syndrome is a PD-like syndrome caused by mutation of a ATP13A2, which encodes a lysosomal ATP-dependent pump with a possible role in Ca2+ transport." (PMID 40279672, 2025). "ATP13A2, also known as PARK9, is a P5-type lysosomal ATPase with mutations that have been linked to Kufor-Rakeb syndrome, an autosomal recessive, juvenile-onset form of PD characterized by parkinsonism." (PMID 41154752, 2025). "Pathogenic variants in ATP13A2 define Kufor–Rakeb syndrome (KRS) and are distinct from other PARK genes, which engage in ubiquitin-proteasome pathways, mitochondrial quality control, or synaptic vesicle recycling." (PMID 41306646, 2025). "Variants in ATP13A2 were firstly associated in 2006 to Kufor‐Rakeb syndrome (OMIM 606693), also known as Parkinson disease 9 with dementia (PARK9), and were later identified in neuronal ceroid lipofuscinosis patients." (PMID 39935284, 2025). "Herein, we describe an Atp13a2 KO rat model, enabling the study of Kufor-Rakeb Syndrome (KRS), an early-onset form of PD associated with impaired ALP functions." (PMID 41253848, 2025). "Kufor–Rakeb syndrome (KRS) is an autosomal-recessive form of early-onset parkinsonism caused by pathogenic variants in the ATP13A2 (PARK9) gene." (PMID 41306646, 2025). "Mutations in the ATP13A2 gene were primarily identified as the cause of Kufor-Rakeb syndrome (KRS), a juvenile-onset form of PD." (PMID 39090150, 2024). "Although initially thought to be a PD locus, mutations in ATP13A2 are now considered to produce the parkinsonian features associated with Kufor–Rakeb syndrome following striatal degeneration." (PMID 37644186, 2024). "Biallelic (autosomal recessive) pathogenic variants in ATP13A2 cause a form of juvenile-onset parkinsonism, termed Kufor-Rakeb syndrome." (PMID 39023817, 2024). "Familial ATP13A2 mutations are also linked to related neurodegenerative diseases, including Kufor-Rakeb syndrome, hereditary spastic paraplegias, neuronal ceroid lipofuscinosis, and amyotrophic lateral sclerosis." (PMID 39030200, 2024). "Mutations in the ATP13A2 gene have been associated with autosomal recessive levodopa-responsive early-onset parkinsonism, or Kufor–Rakeb syndrome (KRS)." (PMID 38534746, 2024). "This particular ATP13A2 variant had previously been classified as a VUS within the context of juvenile-onset PD syndrome (Kufor-Rakeb syndrome) in the ClinVar Miner database (ClinVar; SCV000351396)." (PMID 38783254, 2024). "ATP13A2 (PARK9) gene mutations cause Kufor–Rakeb syndrome (Parkinson’s disease 9), an autosomal recessive form of Parkinsonism with dementia." (PMID 37892117, 2023). "Mutations in the ATP13A2 gene were associated to the Kufor–Rakeb syndrome (KRS), an early-onset autosomal recessive form of Parkinson’s disease with dementia." (PMID 37762226, 2023). "CLN12, also known as Kufor-Rakeb syndrome (PARK9), is caused by loss-of-function variants in the predominantly neuronal P-type ATPase gene, ATP13A2." (PMID 37759536, 2023). "Mutations in ATP13A2 cause Kufor-Rakeb syndrome (Parkinson’s disease 9), an autosomal recessive form of Parkinsonism with dementia." (PMID 37080960, 2023). "Genetic variants in the ATPase Cation Transporting 13A2 (ATP13A2) gene, located on chromosome 1, have been previously associated with Kufor-Rakeb syndrome, spastic paraplegia type 78, and parkinsonism." (PMID 37024536, 2023).
Kufor-Rakeb syndrome (continued). "Mutations in the human ATP13A2 (PARK9), a lysosomal ATPase, cause Kufor-Rakeb Syndrome, an early-onset form of Parkinson’s disease (PD)." (PMID 37080960, 2023). "Pathogenic variants in the ATP13A2 gene are responsible for Kufor-Rakeb syndrome (KRS), an AR atypical form of PD." (PMID 38020640, 2023). "Mutations in ATP13A2 are associated with Kufor–Rakeb syndrome (KRS), an autosomal recessive form of juvenile-onset, atypical PD, known as PD-9." (PMID 36675288, 2023). "Kufor-Rakeb syndrome (KRS) is a genetic disease caused by ATP13A2 (PARK9) mutations that manifests as Parkinson’s disease (PD)." (PMID 36979351, 2023). "Mutations in ATP13A2 can cause early-onset autosomal recessive PD with dementia, pyramidal degeneration, and Kufor-Rakeb syndrome (KRS)." (PMID 35795234, 2022). "Another form of PD, the Kufor–Rakeb syndrome, is linked to mutations in ATPase cation transporting 13A2 (ATPase 13A2), encoding for lysosomal ATPase." (PMID 35684025, 2022). "For example, Kufor-Rakeb syndrome (KRS) is caused by an autosomal recessive mutation in the PARK9 gene encoding ATP13A2 (transmembrane lysosomal type 5 P-type ATPase protein) characterized by juvenile-onset parkinsonism." (PMID 35250476, 2022). "Recessive mutations in ATP13A2 (polyamine-transporting ATPase 13A2), a gene located in a PD-associated locus PARK9, have been identified as the genetic cause for Kufor-rakeb syndrome (KRS), which is a type of Parkinsonian syndromes." (PMID 34194386, 2021). "Different mutations in the ATP13A2 gene have been shown to be involved in different neurodegenerative diseases including Kufor–Rakeb syndrome, early-onset PD, hereditary spastic paraplegia, neuroid ceroid lipofuscinosis, and amyotrophic lateral sclerosis." (PMID 33799982, 2021). "For example, ATP13A2 mutations are known to cause Kufor-Rakeb syndrome, neuronal ceroid lipofuscinosis and neurodegeneration with brain iron accumulation (NBIA)." (PMID 33646413, 2021). "ATP13A2, a late endo-/lysosomal polyamine transporter, is implicated in a variety of neurodegenerative diseases, including Parkinson’s disease and Kufor–Rakeb syndrome, an early-onset atypical form of parkinsonism." (PMID 33799982, 2021). "Homozygous or compound heterozygous mutations in the ATP13A2 gene lead to the development of the CLN12 (Kufor‐Rakeb syndrome) with juvenile onset." (PMID 32412666, 2020). "Mutations in ATP13A2 are discovered in sporadic PD patients and Kufor–Rakeb syndrome (KRS), a rare early-onset atypical parkinsonism with pyramidal degeneration and dementia and autosomal recessive inheritance." (PMID 32650609, 2020). "Mutations in ATP13A2, a transmembrane endo/lysosomal P‐type transport ATPase, cause Kufor–Rakeb syndrome (PARK9), a rare subtype of juvenile‐onset autosomal recessive parkinsonism." (PMID 32767426, 2020). "The PARK9 gene encodes the protein ATP13A2, a transmembrane lysosomal type 5 P-type ATPase, which has been linked to a neurodegenerative disorder known as Kufor–Rakeb syndrome (KRS), as well as to some juvenile and early-onset forms of PD." (PMID 31963435, 2020). "Mutations in ATP13A2, known to cause Kufor–Rakeb syndrome (KRS), have been recently implicated in HSP." (PMID 31944623, 2020). "Subsequent to the identification of ATP13A2 as a causative gene for Kufor-Rakeb syndrome, a homozygous p.Met810Arg allele was reported in a Belgian family with a juvenile-onset neuronal ceroid lipofuscinosis." (PMID 30992063, 2019). "Postmortem pathological examination of the brain tissues from a Kufor-Rakeb syndrome patient with homozygous missense mutations in the ATP13A2 gene showed extensive deposition of lipofuscin in the retina, cerebral cortex, basal ganglia and cerebellum." (PMID 30651094, 2019).
Kufor-Rakeb syndrome (continued). "Apart from loss-of-function mutations that cause Kufor-Rakeb Syndrome, several other mutations in ATP13A2 have been identified involved in a variety of other devastating diseases, including neuronal ceroid lipofuscinosis, PD and amyotrophic lateral sclerosis." (PMID 31393918, 2019). "By contrast, ATP13a2 proteins containing Kufor-Rakeb Syndrome disease-causing mutations fail to reach the lysosome and are instead prematurely degraded in the endoplasmic reticulum (ER) by the ER-associated degradation pathway." (PMID 31393918, 2019). "Mutations in ATP13A2 cause Kufor-Rakeb syndrome (KRS), a juvenile form of Parkinson’s disease (PD) with dementia." (PMID 31393918, 2019). "Loss-of-function mutations in ATP13A2/PARK9 cause Kufor–Rakeb syndrome (KRS), a disorder characterized by juvenile-onset parkinsonism and cognitive decline." (PMID 31450727, 2019). "Mutations in ATP13A2 cause juvenile parkinsonism with dementia, also known as Kufor-Rakeb syndrome (KRS)." (PMID 31393918, 2019). "Although ATP13A2’s function in mammalian cells remains elusive, loss-of-function mutations in ATP13A2 cause Kufor-Rakeb Syndrome (KRS), an autosomal recessive form of early-onset Parkinsonism with pyramidal degeneration and dementia." (PMID 31293375, 2019). "First, loss-of-function mutations in the ATP13A2 gene, which is also called PARK9, have been found in families with a rare hereditary form of juvenile-onset parkinsonism, called Kufor–Rakeb syndrome." (PMID 32714591, 2018). "Originally, ATPase type 13A2 (ATP13A2) has been reported associated with Kufor–Rakeb syndrome (KRS), which is a severe early-onset PD, inherited in an autosomal recessive manner." (PMID 29700661, 2018). "ATP13A2 (ATPase 13A2) is a lysosomal type 5 P-type ATPase mutated in the Kufor-Rakeb syndrome, a juvenile form of Parkinsonism presenting with dementia." (PMID 28202669, 2017). "ATP13A2 mutations are associated with Kufor-Rakeb syndrome (KRS), a form of recessively levodopa-responsive inherited atypical Parkinsonism." (PMID 27896429, 2017). "Specifically, the diagnosis of UDP_6392 with Kufor-Rakeb syndrome (OMIM:606693) was based on clinical correlation with the biallelic ATP13A2 mutation resulting in ATP13A2 ranking as the top candidate of 107 genes." (PMID 26562225, 2016). "We identified 12 different additional rare variants evenly distributed within six different PD genes, including five different ATP13A2 non-Kufor-Rakeb syndrome (KRS) variants, in our LRRK2-positive cohort." (PMID 27798102, 2016). "The late endo-/lysosomal P-type ATPase ATP13A2 (PARK9) is implicated in Parkinson's disease (PD) and Kufor-Rakeb syndrome, early-onset atypical Parkinsonism." (PMID 27073711, 2016). "Mutations in ATP13A2 are associated with PD and Kufor-Rakeb syndrome, which is a severe early-onset autosomal recessive form of PD with dementia." (PMID 27073711, 2016). "Kufor–Rakeb syndrome (KRS) is a rare autosomal recessive inherited juvenile parkinsonian syndrome caused by a frame-shift mutation in exon 22 in ATP13A2 (c.2473C>AA, p.Leu825AsnfsX32)." (PMID 27829488, 2016). "The significance of ATP13A2 also known as PARK9 in PD has increased with the finding that mutations in this gene cause Kufor-Rakeb syndrome (KRS) which is an autosomal recessive, juvenile-onset form of parkinsonism." (PMID 26988916, 2016). "Mutations in ATP13A2 lead to Kufor‐Rakeb Syndrome, which is a disease exhibiting juvenile onset parkinsonism and dementia (PARK9), neuronal Ceroid‐Lipofuscinosis and NBIA." (PMID 25870938, 2016). "For example, compounds that enhance the enzymatic activity or increase the expression of ATP13A2 enzyme, a protein associated with Parkinson’s disease 9 (PARK9), would increase the clearance of accumulated α-synuclein via the lysosomal pathways." (PMID 26317803, 2015).